C19orf33 (chromosome 19 open reading frame 33)
Synonyms: H2RSP; IMUP; IMUP-1; IMUP-2
Tractability: Antibody: its Gene Ontology location is reachable by antibodies, with high confidence. PROTAC: ubiquitination databases record sites on it.
Gene: Protein-coding gene on chromosome 19 (38,304,164 to 38,305,006, forward strand). Ensembl gene ENSG00000167644.
Subcellular location: Nucleus
Subcellular location (Human Protein Atlas): Nucleoplasm; Cytosol; Plasma membrane
Gene Ontology:
Cellular component: nucleoplasm; nucleus; nucleolus
Genetic constraint (gnomAD): Loss-of-function variants: 10 observed, 10.02 expected, observed/expected ratio (o/e) 1, 90% interval 0.61 to 1.65. The upper end of that interval is the gene's LOEUF score, 1.65, which puts it in group 6 of 6, group 1 being the genes least tolerant of losing a copy. Missense variants: 145 observed, 136.18 expected, observed/expected ratio (o/e) 1.06, 90% interval 0.93 to 1.22. Synonymous variants: 61 observed, 52.31 expected, observed/expected ratio (o/e) 1.17, 90% interval 0.95 to 1.44.
Homologues: Orthologues: chimpanzee C19H19orf33 (98% identical), macaque C19orf33 (86% identical), mouse 2200002D01Rik (58% identical), rat C1h19orf33 (58% identical).
Diseases named in the same sentence as C19orf33 in open-access papers:
C19orf33 is named in the same sentence as 9 diseases in open-access papers, as found by Europe PMC text mining. Sharing a sentence is not in itself a finding about the gene and the disease. The quoted sentences say what the papers report.
breast carcinoma (2 papers, 2023). "C19orf33 and its closely related markers have significant roles in multifocal and multicentric breast cancer (MMBC) and, therefore, can be used as markers for MMBC." (PMID 37168445, 2023).
colorectal adenocarcinoma (1 paper, 2015). The most common type of colorectal carcinoma. "An enhanced expression with higher levels in LN positive tumors has been observed for C19orf33 in colorectal adenocarcinoma cells at the invasive front." (PMID 25922907, 2015).
ovarian carcinoma (1 paper, 2015). A malignant neoplasm originating from the surface ovarian epithelium. "Regarding the LVI tumors, the most upregulated gene in the LVI-positive group compared to the negative group was C19orf33 which is also known as IMUP (immortalization upregulated protein), a gene previously shown to be overexpressed in lung, colon, and ovarian carcinoma cell lines." (PMID 25391423, 2015).
pancreatic cancer (1 paper, 2023). "Studies have shown aberrant C19orf33 expression in several cancers, including pancreatic cancer, and is closely related to the patient’s prognosis." (PMID 37397364, 2023).
tumor (5 papers, 2020 to 2024). "The co‐expression of any 1 gene from Group A (C19orf33, S100A14, and RHOD; count ≥1) and any 1 gene from Group B (CST6, CD44, TM4SF1, and TACSTD2; count ≥1) in a single tumor cell was defined as a MIC." (PMID 38864342, 2024).
cancer (4 papers, 2020 to 2023). A tumor composed of atypical neoplastic, often pleomorphic cells that invade other tissues. "Our data suggested that C19orf33 expression may be a general biomarker for the sensitivity of cancer cell lines to many chemotherapeutic agents." (PMID 33858332, 2021).
C19orf33 also shares sentences with these, for which no sentence is quoted: endometrial carcinoma (1 paper); lung carcinoma (1); papillary thyroid carcinoma (1).